TGFB1 (transforming growth factor beta 1)
Diseases named in the same sentence as TGFB1 in open-access papers (continued):
Sharing a sentence is not in itself a finding about the gene and the disease.
tumor (continued). "IFNγ, TNFα, and TGFβ1 are known to induce genotoxic stress, DDR signaling and senescence in both normal and tumor cells and we hypothesized that the JAK2V617F+ P-ECs are refractory to such treatment." (PMID 30967632, 2019). "Our study leverages data from plasma RNA and CTCs, published studies and focused data mining, to propose a testable model in which high concentration of PF4 induces platelet attraction into the tumor microenvironment and regulates expression and/or availability of CLU, CCL5, TGFB1, SRGN and SPARC." (PMID 31215484, 2019). "Mechanistic studies indicated that YFTL could suppress the angiogenesis and the epithelial-mesenchymal transition (EMT) of the tumor through Akt/ERK1/2 and TGFβ1/Smad2 pathways." (PMID 30781674, 2019). "Given that autocrine TGFB1 signaling is essential to sustain stemness and high tumorigenicity of GBM-initiating cells, possible paracrine effects of cytokines released by resident MSC in the tumor stroma must be addressed." (PMID 29872504, 2018). "Here, TGFB1 secreted by MSC was also capable of enhancing U87MG cell proliferation and viability, suggesting the importance of paracrine effects of this regulatory cytokine when produced by other cell types in the tumor microenvironment." (PMID 29872504, 2018). "Again, injections of GBM cells with either control MSC or TGFB1-deficient MSC generated tumors at similar rates, with no significant changes in final tumor size and weight." (PMID 29872504, 2018). "Furthermore, HCQ up-regulated the expression of Ifng and down-regulated the mRNA levels of Tgfb1 and IL10 in tumour-infiltrating CD8+ T cell from tumour tissues." (PMID 30373678, 2018). "Finally, the most significant upstream factor predicted to be inhibited is the growth factor TGFβ1, confirming the relation between BAG3 silencing and tumor growth repression." (PMID 29487711, 2018). "A twofold increase (RQ = 2.313) in TGFB1 mRNA was observed in tumor tissues compared to adjacent normal tissues in female patients in contrast to male patients." (PMID 30071009, 2018). "Interestingly, Gr-1+CD11b+ cells from treated 4T1 tumor-bearing mice showed a decreased expression of ARG1, TGFβ1, and IL-10, factors that are critical in mediating immune suppression in Gr-1+CD11b+ cells." (PMID 29973593, 2018). "In this context, TGFβ1 and MET form key players and act on both cancer cells and the tumor stroma." (PMID 30004628, 2018). "Overall, TGFB1 was significantly upregulated in distant metastases calibrated to both non-tumoral tissues (RQ = 3.655; p = 0.007) and primary tumor tissues (RQ = 2.639; p = 0.026)." (PMID 30071009, 2018). "We studied a retrospective cohort of 160 consecutive surgically treated NSCLC patients with available frozen tumor samples for expression of EMT markers (CDH1, CTNNB1, CDH2, and VIMENTIN), inducers (TGFB1, c‐MET, and CAIX), and transcription factors (EMT‐TF:SNAI1, SNAI2, ZEB1, TWIST1, and TWIST2)." (PMID 29845746, 2018). "In addition, fibroblast proliferation and mesenchymal cell proliferation were significantly enriched GO terms; the expression levels of TGFβ1, S100A6, PDGFA, and BMP7 were enriched in organoids (and tumor), compared with fetal retina." (PMID 30353124, 2018). "Moreover, expression of transforming growth factor β1 (TGFβ1) and fibroblast growth factor 2 (FGF2) even decreased in ASC.B6, opposing to the increased tumor growth promoting effect." (PMID 30185144, 2018). "After inhibition of Tgfb signaling, our zebrafish model showed downregulation of pro-tumor gene expression profiles in TANs and TAMs, indicating that the activated HSC-produced Tgfb1 could have feedback activation of TANs and TAMs." (PMID 29855567, 2018). "As we observed a correlation between TGFB1, chemokines, and immune cells in the human TCGA dataset, we hypothesized that CD8+ T cells might be a candidate for attenuating tumor growth and contributing to long-term cures in the A375 model." (PMID 28448494, 2017).
tumor (continued). "TGFβ1 expression in CRC cells, and its level in the cell medium and extracellular matrix was increased in primary tumour CRCs overexpressing TG2 and could regulate TG2 expression and EMT by both canonical (RKO) and non-canonical (RKO and SW480) signalling." (PMID 28223538, 2017). "Interestingly, we identified FAM101B, a TGFβ1 signaling effector, as a potential downstream effector of NUSAP1 in tumor progression." (PMID 28404898, 2017). "Most of the downregulated genes, including SRC, TGFB1, MMP9 are known to promote tumor metastasis." (PMID 28977939, 2017). "Furthermore, genes reported to promote tumor metastasis in various cancers, including SRC, TGFB1 and MMP9, were upregulated by CTCF." (PMID 28977939, 2017). "Likewise, that group also provided limited data that TGFβ1 overexpression results in SMAD7 activation, which leads to β-catenin/VEGF-A signaling and tumor neo-angiogenesis." (PMID 27895310, 2017). "We first investigated whether a miR-122-mediated repression of TGFβ1/TGFβR1 affected an epithelial–mesenchymal transition (EMT), one of the initiating steps of primary tumour invasion." (PMID 26987776, 2016). "Twenty-eight days after shNRP-1 minicircle delivery, rats demonstrated modest but significant NRP-1 knockdown along with basal increase in the endothelial markers, down-regulation of mesenchymal markers and TGFβ1-responsive Slug and CTGF expression and reduced tumor fibrosis." (PMID 27542226, 2016). "Others have shown that TGFβ1 alters the differentiation program of DC precursors, leading to the development of myeloid-derived suppressor cells (MDSC) that are known to promote tumor outgrowth through a variety of mechanisms." (PMID 27589814, 2016). "Of great importance, for the first time in OS, we show that elevated levels of IL-6 and TGFβ1 are provided by stromal cells, rather than tumor cells and highlight the importance of taking into careful consideration the non-tumor component of the malignancy." (PMID 27851822, 2016). "However, at a later stage, CAFs become activated by several tumor-secreted factors, such as TGFβ1, PDGFα/β, basic fibroblast growth factor (b-FGF), or interleukin 6 (IL-6), resulting in the promotion of both tumor growth and progression." (PMID 27270649, 2016). "Up‐regulation of mRNA markers of inflammation and fibrosis have been previously reported in the fibrotic nontumor tissues 11, 45, as well as in tumor tissue in the present study (Tnf, Tgfβ1, Tgfbr1, and Tgfbr2)." (PMID 26778414, 2016). "Interestingly, positive correlations between the mRNA levels of TGFBR2 and the mRNA levels of TGFB1 (Spearman’s rho = 0.51, P = 5.6 × 10−5, P’ = 5.6 × 10−4) and TGFB3 (Spearman’s rho = 0.42, P = 0.0012, P’ = 0.012) were observed in the tumours (n = 59)." (PMID 26703884, 2015). "Gene expression analysis in pretumor mammary glands showed that all growth factors and chemokines observed to be elevated before tumor development in continuous HFD mice at 13 weeks of age (i.e., Tgfa, Ccl1, Ccl17, Ccl20, Ccl22, and Tgfb1) were elevated in LFD-HFD mammary glands at this time." (PMID 26526858, 2015). "TGFβ1 expression was not correlated to any of the traditional prognostic markers such as age, tumor size, SBR grade, axillary lymph node metastasis, ER, PR, and HER2 status." (PMID 26040677, 2015). "TGFB1 mRNA expression was seemly lower in triple-negative tumours and in tumours from lymph node-negative patients." (PMID 26703884, 2015). "In the tumour microenvironment, TAMs resemble M2-macrophages and induce the production of a large range of growth factors and proteolytic enzymes such as EGF, TGFβ1, VEGE and MMPs to stimulate ECM degradation, thus promoting tumour metastasis, resulting in poor cancer prognosis." (PMID 25692297, 2015).
tumor (continued). "The hMSC promoted tumor cells proliferation by secreting several factors, including basic fibroblast growth factor (bFGF), platelet derived growth factor B (PDGF-BB), transforming β growth factor 1 (TGFβ-1), and vascular endothelial growth factor (VEGF)." (PMID 26003220, 2015). "Therefore, based on the hMSC is a good carrier for gene, our aim is to observe effects of the exogenous TGFβ-1 by gene modified hMSC experission on HCC in vitro, especially on the proliferation and invasion ability of tumor tissue or tumor cells." (PMID 26003220, 2015). "Hence, we report that galectin-3 disruption in tumor stroma and parenchyma decreases angiogenesis through interfering with the responses of macrophages to the interdependent VEGF and TGFβ1 signaling pathways." (PMID 24421272, 2014). "Decreased expression of galectin-3 in either compartment may lead to impaired tumor angiogenesis, as we have observed experimentally, as a result of diminished VEGF and/or resistance to TGFβ1." (PMID 24421272, 2014). "We investigated thyroid hormones levels in menopausal BrC patients because of their lack of estrogen and verified the action of T3 on genes regulated by E2 (TGFA, TGFB1, and PGR) and T3 (TNFRSF9, BMP6, and THRA) in primary BrC tissues exhibiting the early stages of tumor progression." (PMID 24701358, 2014). "The supernatant of SCL-1 tumour cells and TGFβ1 triggered a rapid increase in intracellular ROS levels in HDF leading to an impaired gap junctional intercellular communication, a prerequisite for tumour progression." (PMID 27919042, 2014). "Culture of purified monocytes with 72-h tumor cell line CM showed that 6 of 15 CM also stimulated the secretion of TGFβ1 by monocytes after 24 h (data not shown)." (PMID 23982484, 2013). "HCC tumor has shown to secret a lot of cytokines related to the development of the tumor, like vascular endothelial growth factor (VEGF), transforming growth factor-beta 1 (TGF-β1), Interleukin 8 (IL-8), or tumor-specific growth factor (TSGF)." (PMID 22690340, 2012). "Our objective is to study the biological effects of low energy protons on epithelial cells and its propensity to enhance transforming growth factor beta 1 (TGFβ1)-mediated epithelial-mesenchymal transition (EMT), a process occurring during tumor progression and critical for invasion and metastasis." (PMID 22844446, 2012). "Taking together, our studies suggest that proton radiation, an advanced choice for deep-seated tumor treatment, may trigger EMT, and enhance TGFβ1–mediated EMT in normal tissues, even following a single acute low dose." (PMID 22844446, 2012). "Overexpression of TGFB1 in those triple-negative tumors with poor prognosis may thus induce EMT and enhance the aggressiveness of tumor behavior." (PMID 23049873, 2012). "We provide evidence that the aberrant activation of TGFβ1 in the tumor microenvironment lacking stromal-derived SPARC contributes significantly to the phenotypic alterations observed during progression of orthotopic Pan02 tumors." (PMID 22348081, 2012). "In addition, an ELISA specific for active TGFβ1 was performed on SPARC+/+ and SPARC−/− tumor lysates." (PMID 22348081, 2012). "The study aimed to evaluate, during colorectal carcinogenesis from benign to malignant phases: i) the trend of serum levels of IL-8, IL-6, TGFβ1, VEGF and MMPs; ii) the parallel trend of CRP serum levels; iii) derangement of the principal TGFβ1 receptors (TGFβ1RI/RII) in tumor tissues." (PMID 22848630, 2012). "Although losartan was able to effectively reduce the expression, activation and signaling of TGFβ1, further validation is needed to prove that it is through the inhibition of TGFβ1 and not angiotensin II that tumor progression is reduced in SPARC−/− mice." (PMID 22348081, 2012). "It is possible that elevated TGFβ1 by itself acts as a tumor promoter, although this has not been directly demonstrated." (PMID 23326666, 2012).
tumor (continued). "In addition, in TGFβ-1 treated LC31 cell line, an increased pneumosphere-forming capacity and tumours-forming ability in NOD/SCID mice were detectable." (PMID 21738704, 2011). "TGFB1 (transforming growth factor-β, TGF-β) and its receptor TGFBR2 constitute a signaling pathway that regulates the transcription of many genes, and functions as a tumor suppressor and an immune response regulator." (PMID 21949851, 2011). "Dendritic cells present in negative SLN appear to be more tolerogenic than those within the primary tumour because, although the median expression of ILT3 remains stable, the expression of both IDO and TGFβ1 increases by as much as a factor of 30 in matched samples." (PMID 17565341, 2007). "The prognostic significance of high TGFβ1 level on DFS observed in node-negative breast cancer patients suggest that the determination of tumoral TGFβ1 status might help to identify a high-risk population early in tumour progression, for which a more appropriate therapy should be established." (PMID 16404434, 2006). "The fact that prognostic value of TGFβ1 was observed in node-negative population strongly suggests that TGFβ1 interferes at early stages of tumour progression, probably by making cell environment favorable for metastatic spread." (PMID 16404434, 2006). "Desmoid tumour is a benign non-invasive and non-metastasising neoplasm with an abnormal ECM macromolecule deposition which is stimulated by TGFβ1." (PMID 15740610, 2005). "Additionally, positive correlations with TGFB1 and ADORA2A highlight a highly immunosuppressive tumor microenvironment that could further inhibit effective anti-tumor responses." (PMID 41293172, 2025). "Finally, we examined whether elevated TGFβ1 and CXCL12 levels mediate the tumor‐promoting effects of exosomal CMTM4 in OC." (PMID 40433989, 2025). "The activation of TGF-β signalling led to increased downstream gene expression, as indicated by the correlation of SMAD7 expression—a typical SMAD-positively regulated gene—with TGFB1 in human iCCA and the increased Smad7 mRNA expression in tumours from the mouse iCCA models." (PMID 40820091, 2025). "Rather than suppressing tumor growth, TGFβ1 may interfere with the activity of NK cells by activating or inhibiting specific mechanisms that disrupt the expression of activating receptors and alter cellular metabolism." (PMID 40710292, 2025). "Given the excellent efficacy of the triple treatment in inhibiting tumor progression, it is not surprising to us since TGFβ-1, IL-1β, and IL-10, and IL-30 are key mouse Th2, Th17, and Treg differentiation cytokines that have been linked to immune suppression during cancer development." (PMID 40104170, 2025). "Moreover, GPR176 may influence the immune status of the tumor microenvironment in STAD by regulating the immunosuppressive function of TGFB1 and the chemotactic activity of CXCL12, further affecting tumor progression." (PMID 40689396, 2025). "Similarly, in human umbilical cord-derived MSCs (hUC-MSCs), transfection with miR-3940-5p mimics led to EVs that suppressed EMT, invasion, metastasis, and tumor progression by targeting integrin subunit alpha 6 (ITGA6) and inhibiting the transforming growth factor beta 1(TGF-β1) pathway." (PMID 41254732, 2025). "Notably, TGFB1, TGFB2, TGFB3, S100A8, S100A9, IL6, and PTGES secreted by PMN-MDSCs exhibit both protumorigenic and immunosuppressive properties, playing significant roles in promoting tumor growth and evading immune responses." (PMID 41280721, 2025). "In addition, the analysis of human carcinoma tissue sections revealed a significant negative correlation between TGFβ1 and GLUT1 densities within tumor cells and their associated nerve fibers (r = -0.6751)." (PMID 39842382, 2025).
tumor (continued). "Transforming growth factor beta 1 (TGFB1) belongs to the TGF-β subfamily and the TGF-β signaling pathway, which regulates cell fate and plays pleiotropic roles in tumor malignant progression by regulating cell proliferation, apoptosis, migration, and tumor microenvironment (TME)." (PMID 40313933, 2025). "Our mechanistic study revealed that TBC1D1-mediated inhibition of CTL function could be attributed to the upregulation of various immune checkpoint molecules, including ARG1, CD68, PDCD1, CD274, TGFB1, and CTLA4, collectively impeding the anti-tumor immune response." (PMID 38529286, 2024). "Overall, the addition of MDMs to T cell-tumor cell co-cultures induced proinflammatory factors such as TNF secretion, elevated CTLA4 mRNA expression which is known to increase in response to T cell activation and simultaneously decreased anti-inflammatory CCR4 and TGFB1 mRNA expression." (PMID 39414902, 2024). "In the human PDAC patient tumor transcriptome (TCGA), we identify strong and significant correlations between tumoral GHR expression and known lymphangiogenic (LYVE1, FLT4, VEGFC, and PDPN) and angiogenic (PDGFRa, FGFR1, TGFB3, TGFB1, TGFBR2, HIF1a, IL6, and IL1B) markers." (PMID 39000545, 2024). "Finally, TGFB1 was included as a control in our analysis due to consistently high expression levels observed across both tumor and adjacent non-neoplastic tissues in nCounter NanoString data (counts ranging from 340 to 430)." (PMID 38979413, 2024). "Furthermore, an analysis utilizing the TSIDB database uncovered a significant correlation between AEG-1 and several key factors, including the tumor-promoting cell Th2, immune activator IL6, CXCR4, immunosuppressants CTLA4, IL1, IDO1, LAG3, PDCD1, TGFB1, and the DHC molecule HLA-DPA1." (PMID 39483471, 2024). "In addition, TGFB1 promotes recruitment of monocytes into the TME and strongly polarizes monocyte-derived macrophages (M0) into pro-tumoral M2-like macrophages that enable tumour growth, proliferation, angiogenesis, and EMT." (PMID 37370765, 2023). "Similarly, tumor cell invasion in Matrigel-coated Boyden chambers was reduced by NDRG1 knockdown under TGFβ1 treatment only in MDA-MB-231, whereas no changes were detected in SUM159 cells." (PMID 36594086, 2023). "By comparison, high levels of transforming growth factor beta 3 (TGFB3) mRNA expression in tumor samples was associated with significantly better survival outcomes of DIPG patients, whereas high levels of transforming growth factor beta 1 (TGFB1) expression was not prognostic." (PMID 36980562, 2023). "Similarly, the side population was modified only in SUM159 cells, although Multi-Drug Resistance 1 (MDR1), or p-glycoprotein, was reduced in both SUM159 and MDA-MB-231 cells only upon activation with TGFβ1, what endorses the notion that NDRG1 is involved in tumor chemoresistance." (PMID 36594086, 2023). "Furthermore, treatment with TGFβ1 inhibitor, Disitertide, or TGFβ1 receptor inhibitor, LY-364947, significantly inhibited FAM3C expression in neutrophils, and reversed expression of E-cad and Vim in tumor cells, respectively." (PMID 37056931, 2023). "However, the role of TGFβ1 in HCC is complex, as it can also exhibit tumor suppressor functions." (PMID 37957694, 2023). "In the early stages of CRC, statins inhibited angiogenesis, but they could not considerably affect transforming growth factor-beta 1 (TGF-β1) levels in tumor tissue." (PMID 38023258, 2023). "Given that TGFβ1 was found to activate GSK3β (p-GSK3β Tyr216) in MCF10A breast cells and human fibroblasts 36,37, we questioned whether staining of this active form in TNBC tumor tissue, could correlate with NDRG1 and p-NDRG1 staining." (PMID 36594086, 2023). "Thus, we measured the concentration of TGFβ1 in the culture media of monocultured tumor cells, non-activated platelets, platelets activated by thrombin and B16F10-C3 and 231-GFP cells cocultured with non-activated platelets using ELISAs." (PMID 37705745, 2023).